BRCA1 (BRCA1 DNA repair associated)
Diseases named in the same sentence as BRCA1 in open-access papers (continued):
Sharing a sentence is not in itself a finding about the gene and the disease.
breast cancer (continued). "Deregulation of BRCA1 expression has been implicated in sporadic breast cancer." (PMID 25051360, 2014). "PTEN loss is highly associated with BRCA1 breast cancers, which could result from genome instability involving homozygous deletions, DNA double-strand breaks and so on." (PMID 25426449, 2014). "A strong association was found between family history of breast cancer and a high frequency of Aldh1a1 expression in breast ductules in women, regardless of a hereditary breast-ovarian cancer syndrome status (Brca1 and Brca2 mutations), age, parity, or occurrence of cancer." (PMID 24594504, 2014). "However, despite its association with inherited predisposition, somatic disease-causing mutations in BRCA1 or BRCA2 are extremely rare in sporadic breast cancer." (PMID 24591761, 2014). "Analysis of a single family with a history of breast cancer incidence in both males and females revealed two BRCA1 mutations (Q356R andS1512I) which may be associated with the breast cancer phenotype in the family." (PMID 24678344, 2014). "Notably, -132 was the critical site for PEMT transcription only in primary BRCA1-mutated breast cancer cells (Fig. 3Bii)." (PMID 24675476, 2014). "However, malfunction of the first discovered breast cancer sensitivity gene product, BRCA1, has been recognized as the most frequent risk factor for this mammary tumorigenesis." (PMID 24586743, 2014). "We hypothesize that the loss of BRCA1 function could cause genome instability in non-breast cancer cells." (PMID 24884718, 2014). "We next tested the hypothesis that the BRCA1-3’UTR-variant may predict altered breast cancer biology in our Irish cohort of patients." (PMID 24915755, 2014). "The only published study quantifying TL in individuals with breast cancer who carry BRCA1/2 mutations and individuals with sporadic breast cancer showed an association between shorter telomeres in those affected by hereditary cancer, but not in those affected by sporadic breast cancer." (PMID 24489760, 2014). "Moreover, patients with metastatic disease (n = 23) at presentation had a four-fold risk of carrying the BRCA1-3’UTR-variant compared to Stage I breast cancer patients (p = 0.018, OR 3.73, 95% CI 1.26-11.07)." (PMID 24915755, 2014). "Our study shows the presence of mutations in blood cells from the BRCA1+ breast cancer family." (PMID 24884718, 2014). "For example, in phase II trials, 400 mg twice daily exposure of PARPi olaparib only resulted in the delay of breast cancer and ovarian cancer progression (both with median progression-free survival of about six months), and all patients with BRCA1/2 mutations eventually died of cancers." (PMID 24962108, 2014). "The basal like breast cancer cell line HCC9137 harbors a homozygous truncation mutation in the DNA repair gene BRCA1 and this reduced capacity to repair DNA breaks may underlie this cell lines sensitivity." (PMID 25104095, 2014). "Thus the finding that BRCA1/2-associated breast cancers are highly sensitive to PARPi has been considered as a very promising approach for breast cancer." (PMID 24962108, 2014). "We compared HRs for the association with overall breast cancer and ER-positive and ER-negative breast cancer for all the 74 known breast cancer susceptibility variants between BRCA1 carriers, BRCA2 carriers and population-based studies using published data from BCAC." (PMID 25919761, 2014). "Notably, only in BRCA1-mutated breast cancer cells was the E2F1 motif found to be the critical element for DNMT1 transcription (Figure3Bii)." (PMID 24502362, 2014). "Subsequently, the same mutation was identified in BRCA1/2-negative families with hereditary breast cancer and it has been estimated that it results in an approximately two-fold increase of the risk of breast cancer in women and a ten-fold increase of risk in men." (PMID 24986639, 2014).
breast cancer (continued). "Of note, a recent study for the prediction of BRCA1/2 mutation-associated hereditary breast cancer identified a 35-miRNA classifier for the prediction of BRCA1/2 mutation status with a reported 95% and 92% accuracy in the training and the test set, respectively." (PMID 25250326, 2014). "Observational studies and small neoadjuvant studies have also suggested that BRCA1 mutation-associated breast cancers may be more sensitive to platinum agents as compared to sporadic TNBC." (PMID 25177489, 2014). "The risk for breast cancer was 55% to 65% for BRCA1 and 45% to 47% for BRCA2 mutation carriers." (PMID 25136623, 2014). "Also, activation of the phosphoinositide 3-kinase (PI3K) is often associated with the BRCA1-related breast cancers in clinical sample." (PMID 25426449, 2014). "Among women with BRCA1/2 mutations, nearly 50% may be expected to develop breast cancer by age 50 years." (PMID 25159706, 2014). "This would befit its widely accepted role as a major BRCA1 breast cancer risk factor." (PMID 25400221, 2014). "In addition, expression levels of PEMT were decreased in BRCA1-mutated breast cancer compared to their adjacent normal breast tissues." (PMID 24675476, 2014). "As BRCA1 carriers are more likely to develop ER-negative disease, SNPs associated with this subtype will be more informative in models to predict overall breast cancer risk in these women, whereas SNPs associated with ER-positive disease will be more useful in BRCA2 carriers." (PMID 25919761, 2014). "Soon after the identification of the breast cancer predisposition genes BRCA1 and BRCA2, mutation screening of families burdened with a substantial history of breast and ovarian cancer, became a routine demand, since it aids the identification of individuals at high risk." (PMID 24695549, 2014). "Moreover, univariate survival and multivariate analyses indicated that lymph node metastasis was an independent and reliable prognostic factor which is associated with worse outcomes for BRCA1-mutated breast cancer patients." (PMID 24675476, 2014). "BRCA1 is the most frequently mutated tumor suppressor gene in breast cancer." (PMID 25460500, 2014). "Therefore, the search for additional germline variants, outside of the BRCA1 open-reading-frame predicting increased breast cancer risk has been undertaken." (PMID 24915755, 2014). "Breast cancers with a BRCA1 mutation are also frequently triple-negative." (PMID 24507701, 2014). "This is exemplified in cancers with low BRCA1 and ERα, and BRCA1 loss is hypothesized to lead to ERα downregulation in breast cancer." (PMID 24860786, 2014). "Any dysfunction in BRCA1 correlates with greater risk of breast cancer symptoms." (PMID 24997799, 2014). "Interestingly, low BRCA1 mRNA expression identified in sporadic breast cancer specimens has been associated with development of distant metastasis (p = 0.019) and a shorter disease free interval (p = 0.015)." (PMID 24915755, 2014). "A separate signature of chromosomal instability, termed ‘large-scale transitions’ (LSTs), was established by using basal-like breast cancer and cell line data sets in which samples with BRCA1 promoter methylation or BRCA1/2 mutation (germline or somatic) were considered BRCA1/2-inactive." (PMID 25093514, 2014). "However, no expression differences for different transcripts between non-BRCA1-mutated breast cancer and their adjacent normal breast tissues were observed." (PMID 24675476, 2014). "Women who inherited BRCA1+ have a 60-80% risk of developing breast cancer by the age of 70." (PMID 24884718, 2014). "The current study strongly suggested that the low and recessive population-specific genetic variant rs3734091 of XRCC4 may influence the risk of non-BRCA1/2 breast cancer, which could be missed by routine GWAS analyses of women of European ancestry." (PMID 25360583, 2014). "In addition, it has been estimated that BRCA1 mutation carriers have a 50 to 80% risk of developing breast cancer before the age of 70 years." (PMID 24962108, 2014).
breast cancer (continued). "Approximately 5% of all breast cancers can be attributed to a mutation in the BRCA1 or BRCA2 gene." (PMID 24742220, 2014). "BRCA1/2 deleterious mutations were observed in all breast cancer subtypes." (PMID 25475740, 2014). "The concordance among these studies in early-onset breast cancer patients strengthens the hypothesis that young Brazilian women with a positive family history are at high risk of being BRCA1/2 carriers." (PMID 24884479, 2014). "Additionally, a high level of heterogeneity in loss of heterozygosity (LOH) was observed in breast cancer with BRCA1/2 heterozygotes." (PMID 25158060, 2014). "This may be due to rs2046210 being independently associated with the risk of BC for BRCA1 mutation carriers while breast cancer patients with BRCA1 mutations are more often estrogen receptor negative." (PMID 25531440, 2014). "An early age at Breast Cancer (BC) onset may be a hallmark of inherited predisposition, but BRCA1/2 mutations are only found in a minority of younger BC patients." (PMID 24498881, 2014). "Furthermore, functional HIF-1α overexpression (mostly hypoxia induced) is seen at a much higher frequency in BRCA1 mutation-related invasive breast cancer than in sporadic breast cancer." (PMID 23409121, 2013). "Given the similarities between BRCA1-associated breast cancers and TNBC, it has been suggested that TNBC may be sensitive to therapeutic strategies that target DNA repair mechanisms." (PMID 24063698, 2013). "Moreover, this topic has been analyzed in a previous meta-analysis, that demonstrated an increased breast cancer risk in BRCA1/2 mutation carriers for individuals with both alleles C29 polyglutamine repeat." (PMID 23483928, 2013). "So, DIM may prevent breast cancer development in patients with heterozygous inherited and sporadic BRCA1 gene mutations." (PMID 24325835, 2013). "With respect to BRCA1, which is mutated in four of the ER-negative cell lines, we identified 13 miRNAs being differentially expressed between four mutant cell lines and 12 wild-type breast cancer cell lines." (PMID 23601657, 2013). "In FFPE specimens, more uniform nuclear staining was observed in benign breast, invasive lobular cancers, and low grade ductal cancer, while less or absent staining was found in the majority of high-grade ductal carcinomas and breast cancer tissue from patients with BRCA1 185 del AG mutations." (PMID 23855721, 2013). "From 16 susceptibility variants selected for analysis, four SNPs, representing three different loci, significantly associated (p-valuecor < 0.05) with breast cancer risk, both in group of all cases as in sporadic and familial cancer subgroups, and after exclusion of BRCA1 mutation carriers." (PMID 24171766, 2013). "The biological function of TopBP1 and its close relation with BRCA1 prompted us to investigate whether alterations in the TopBP1 gene can influence the risk of breast cancer." (PMID 23277395, 2013). "MRI is more sensitive than mammography for breast cancer screening in BRCA1/2 mutation carriers, with screening trials indicating that between 89-100% of breast cancers were detected with the combination of mammography and MRI, versus 33-50% with mammography alone." (PMID 23837641, 2013). "It has been suggested that platinum may be an effective drug treatment for breast cancer with genetic mutations in the BRCA1 gene." (PMID 23426861, 2013).
breast cancer (continued). "Based on piecewise Weibull model and in a kin-cohort analysis, we have found that the BRCA1/2 mutations penetrance seems to be lower among Iranian breast cancer families as it was reported 31.9% and 46.2% for women aged lower and more than 50 years old, respectively." (PMID 24312913, 2013). "Also, significant modification of breast cancer risk in BRCA1/2 mutation carriers was observed in association with selected low-penetrant risk alleles." (PMID 24171766, 2013). "In this scenario, it could be hypothesized the evaluation of novel combination therapies (i.e. DNA damaging agents plus anti-angiogenic drugs) in subgroup of breast cancer patients carrying BRCA1-2 mutations." (PMID 23326384, 2013). "Interestingly, loss of BRCA1 accompanied with Myc over-expression accelerates breast cancer development, especially basal-like breast cancer." (PMID 24040146, 2013). "Similarly, the breast cancer susceptibility gene, BRCA1, has been shown to modulate miRNA biogenesis." (PMID 23696749, 2013). "The biological function of TopBP1 and its close relation with BRCA1 prompted us to investigate whether genetic alterations in the TopBP1 gene can influence the risk of breast cancer." (PMID 23277395, 2013). "BRCA1 promoter hypermethylation has been implicated as one of the mechanisms of loss of gene expression and has been identified in 9–32% of unselected sporadic breast cancer." (PMID 23405268, 2013). "Consistent with the Knudsen model, inactivating mutations of both BRCA1 alleles are uncommon in sporadic breast cancers, since the probability of two acquired hits in a somatic cell is much lower than that of a second hit in a cell that has already acquired the first hit by inheritance." (PMID 23802008, 2013). "Recently, genome wide association studies (GWAS) have also focused on the contribution of both BRCA1/2 gene alterations and genetic modifiers which could increase hereditary predisposition to breast cancer." (PMID 24179442, 2013). "However, family history of breast cancer remains a predictive risk factor, after carrier status for BRCA1 and/or BRCA2 mutations has been investigated." (PMID 23326384, 2013). "Moreover, a subset of BRCA1-deficient breast cancers had lost 53BP1 protein expression, resulting in the HR repair pathway being restored in these cells." (PMID 23761435, 2013). "BRCA1 mutations are associated with a large increase in the risk of breast cancer and our data suggest that miR-335 overexpression may be another mechanism by which the functions of this cancer-associated gene can be modulated." (PMID 23696749, 2013). "Another key point is the therapeutic approach for ER+BRCA1-associated breast cancers." (PMID 24137399, 2013). "Furthermore, BRCA1 mutation carriers who are older or post-menopausal at the time of the diagnosis of breast cancer are more likely to have an ER+ breast cancer." (PMID 24137399, 2013). "Inherited mutations in BRCA1 confer lifetime risks of breast cancer of 70% to 80%." (PMID 23483928, 2013). "This may be of particular significance to breast cancer therapy, as a significant percentage of hereditary breast cancers carry the BRCA1 or BRCA2 mutations and thus are deficient in HR." (PMID 24137461, 2013). "Some studies have demonstrated breast cancer at a younger age might be associated with higher grade, ER-negativity, a more advanced stage of the disease, ectopic expression of BRCA1, and higher levels of HER2." (PMID 23915145, 2013). "Furthermore, the DEABM simulations of BRCA1 mutant patients demonstrated a timeline of cumulative breast cancer risk comparable to that reported in the literature." (PMID 23704974, 2013). "BRCA1 3300delA mutation associates with familial breast cancer in Thai patients." (PMID 23393598, 2013). "It is reasonable to assume that RAD51 and BRCA1/2 mutations may have interactive effects on breast cancer risk." (PMID 24040396, 2013). "In France mutations were found in 15/507 (2.9%) BRCA1/2-negative familial breast cancer cases." (PMID 23806170, 2013).
breast cancer (continued). "The advantage of having mutant BRCA1 human breast cancer cell lines is that the impact of pathogenic human mutations may be evaluated in the context of a human genetic background." (PMID 24137399, 2013). "An initial portrait of the early-onset breast cancer patients in Brazil was generated pointing out that hormone receptor-negative tumors and positive familial history are two major risk factors for detection of a BRCA1 germline mutation." (PMID 23469205, 2013). "Genomic abnormalities resulting in loss of DNA repair function are associated with the development of several tumours, i.e. loss of BRCA1 or BRCA2 genes in hereditary ovarian or breast cancer, or defects in the DNA mismatch repair pathway in hereditary non-polyposis colorectal cancer." (PMID 24244370, 2013). "Interestingly, DNA microarray and immunohistochemical analyses revealed that 80-90% of breast cancers in women with germ-line mutations in BRCA1 are triple-negative." (PMID 29147345, 2013). "BRCA1 mutation carriers face a lifetime risk to develop breast cancer that ranges from 57% to 65%." (PMID 23374397, 2013). "It has been postulated that their phenotypic and molecular similarity to BRCA1-associated breast cancers may prove useful in terms of treatment." (PMID 23426861, 2013). "Certain mutations in BRCA1 significantly increase the risk that a woman will develop breast cancer." (PMID 23840520, 2013). "We present a familial breast cancer case with a BRCA1 mutation as an example." (PMID 23415259, 2013). "This ICER was estimated using local cost and treatment data, with input from clinicians and decision-makers on the project’s advisory panel, in an effort to most accurately depict the context of breast cancer screening and treatment for BRCA1/2 mutation carriers in British Columbia." (PMID 23837641, 2013). "Healthy weight during adult life, particularly from menarche to 21 years, has been associated with decreased breast cancer risk while weight loss between 18 and 30 years of age has been associated 34% reduction in breast cancer risk, particular among BRCA1 mutation carriers." (PMID 23517070, 2013). "On the other hand, differences in the associations of the modifying polymorphisms with breast cancer risk for BRCA1 and BRCA2 mutation carriers are likely to reflect differences in the biology of tumor development in these two groups of women at high risk of BC." (PMID 23483928, 2013). "In addition, a review of BLBC- and BRCA1-associated tumours also states that these tumours are characterised by lower levels of p16 than the typical breast carcinoma." (PMID 23717338, 2013). "Importantly, large genomic rearrangements account for up to 12% of all novel BRCA1 mutations identified in high-risk breast cancer families." (PMID 22347400, 2012). "We previously reported that nonsense-mediated mRNA decay (NMD) could lead to DASE of BRCA1/2, which is associated with elevated susceptibility to breast cancer." (PMID 23107584, 2012).